EML3 (EMAP like 3)
Description:
Regulates mitotic spindle assembly, microtubule (MT)- kinetochore attachment and chromosome separation via recruitment of HAUS augmin-like complex and TUBG1 to the existing MTs and promoting MT-based MT nucleation. Required for proper alignnment of chromosomes during metaphase.
Synonyms: FLJ35827; ELP95; EMAP3; EMAP95
Tractability: PROTAC: ubiquitination databases record sites on it; its protein half-life has been measured.
Gene: Protein-coding gene on chromosome 11 (62,602,217 to 62,612,973, reverse strand). Ensembl gene ENSG00000149499.
Subcellular location: Cytoplasm, cytoskeleton; Cytoplasm; Nucleus; Midbody; Cytoplasm, cytoskeleton, spindle
Gene Ontology:
Molecular function: protein binding; microtubule binding
Biological process: mitotic metaphase chromosome alignment; regulation of mitotic spindle assembly; microtubule cytoskeleton organization
Cellular component: cytoplasm; microtubule cytoskeleton; midbody; mitotic spindle microtubule; nucleus; spindle; spindle microtubule; mitotic spindle; cytoskeleton
Genetic constraint (gnomAD): Loss-of-function variants: 53 observed, 105.81 expected, observed/expected ratio (o/e) 0.5, 90% interval 0.4 to 0.63. The upper end of that interval is the gene's LOEUF score, 0.63, which puts it in group 2 of 6, group 1 being the genes least tolerant of losing a copy. Missense variants: 994 observed, 1,188.5 expected, observed/expected ratio (o/e) 0.84, 90% interval 0.79 to 0.88. Synonymous variants: 499 observed, 484.6 expected, observed/expected ratio (o/e) 1.03, 90% interval 0.96 to 1.11.
Homologues: Orthologues: chimpanzee EML3 (99% identical), macaque EML3 (96% identical), rabbit EML3 (95% identical), mouse Eml3 (94% identical), rat B3gat3 (93% identical), guinea pig EML3 (89% identical), dog EML3 (88% identical), pig EML3 (85% identical), zebrafish eml3 (57% identical), tropical clawed frog eml3 (56% identical). Paralogues in human: EML4 (49% identical), EML1 (45% identical), EML2 (39% identical), EML5 (30% identical), EML6 (29% identical), WDR90 (22% identical), CFAP44 (17% identical), CFAP251 (16% identical), CFAP52 (14% identical).
Diseases named in the same sentence as EML3 in open-access papers:
EML3 is named in the same sentence as 3 diseases in open-access papers, as found by Europe PMC text mining. Sharing a sentence is not in itself a finding about the gene and the disease. The quoted sentences say what the papers report.
asthma (2 papers, 2020 to 2022). "Of the lung function candidate genes, rare variant burden in four genes (MAPT, CFDP1, EML3, and LTBP4) was nominally associated with asthma risk in our study." (PMID 35368043, 2022).
Insulin resistance (1 paper, 2018). Increased resistance towards insulin, that is, diminished effectiveness of insulin in reducing blood glucose levels. "We detected transcription factors CTCF, CTCFL, and Egr1 binding to the genomic region overlapping the differentially methylated CpG within EML3 gene; out of these, CTCF is proved to mediate glucagon production and Egr1 is responsible for insulin resistance." (PMID 30545422, 2018).
pneumonia (1 paper, 2019). An acute, acute and chronic, or chronic inflammation focally or diffusely affecting the lung parenchyma, caused by an infection in one or both of the lungs (by bacteria, viruses, fungi, or mycoplasma.). "Moreover, the expression of eight DEPs (PECAM1, PGLYRP1, AHCY, BHMT, EML3, ICOSLG, IGHV3‐23 and RTN4RL2) in normal and pneumonia groups (two patients) was quite different from that in the KD group." (PMID 30761252, 2019). "Moreover, the expression of eight of these 30 DEPs (PECAM1, PGLYRP1, AHCY, BHMT, EML3, ICOSLG, IGHV3‐23 and RTN4RL2) clustered normal and pneumonia samples into one group and clustered KD samples into another group, which heightens the importance of these eight DEPs in KD." (PMID 30761252, 2019).